GPC1 (glypican 1)
Diseases named in the same sentence as GPC1 in open-access papers (continued):
Sharing a sentence is not in itself a finding about the gene and the disease.
pancreatic cancer (continued). "Since these GPC1+ve exosomes were observed to be 100-175nm in diameter, it is conceivable that other EVs such as microparticles/microvesicles released by pancreatic cancer cells could bear the GPC1 biomarker." (PMID 30800217, 2019). "Similarly, transmembrane GPC-1 promotes proliferation and metastatic growth of pancreatic cancer cells, whereas, soluble GPC-1, inhibits the mitogenic response to FGF-2 and heparin-binding EGF-like growth factor (HBEGF)." (PMID 32010611, 2019). "Besides that, a miRNA signature in circulating TEXs was found to be superior to exosomal GPC1 or plasma CA-199 level in diagnosing pancreatic cancer and identifying PDAC and pancreatic disease from chronic pancreatitis (CP)." (PMID 31438991, 2019). "This gating strategy would allow us to determine the clinical utility of all GPC1+ve EVs, whether they were exosomes, microvesicles/microparticles in identifying patients with pancreatic cancer from patients with benign conditions." (PMID 30800217, 2019). "In recent years, the significant detection function of molecular biomarkers in exosomes has been discovered, since glypican-1 was found to identify cancer exosomes and could detect early pancreatic cancer." (PMID 30733650, 2019). "In this study, knockdown of GPC-1 expression in cells inhibited the mitotic response to fibroblast growth factor−2 (FGF-2), suggesting that GPC-1 might play an important role in the initiation and progression of pancreatic cancer." (PMID 31355137, 2019). "However, a recent study identified exosomes derived from pancreatic cancer cells were enriched with a cell surface proteoglycan, glypican-1 (GPC1)." (PMID 31438991, 2019). "Scientifically, there were reservations about whether GPC-1 could be a real early biomarker of pancreatic cancer." (PMID 30202003, 2018). "Glypican-1 (GPC-1) has been recognized as biomarker of pancreatic cancer." (PMID 30202003, 2018). "While the scientific and clinical discussion of the nature of the GPC-1 related to the stage of the pancreatic cancer continued, nevertheless, many studies showed that GPC-1 was crucial for efficient cancer cell growth, metastasis and in the pathogenesis of diseases." (PMID 30202003, 2018). "We also examined the expression of GPC1 in other pancreatic neoplasms." (PMID 29245923, 2017). "In addition to ESCC, increased expression of GPC1 has been reported in pancreatic cancer, breast cancer and glioma and shown to promote the mitogenic, metastatic and angiogenic properties of cancers." (PMID 28445969, 2017). "Then, we evaluated the existence of tumor-promoting effects of GPC1 in pancreatic cancer in vitro." (PMID 29245923, 2017). "Furthermore, highly accurate quantification of GPC1 mRNA with low copy numbers in serum EVs from pancreatic cancer patients achieved by LPHN–CHDC biochips highlights their clinical potential in early cancer diagnosis and therapeutic monitoring." (PMID 29162835, 2017). "If GPC1 truly serves as a tumor-promoting role in pancreatic cancer as described in earlier reports of the literature, then elucidating the regulation mechanism of GPC1 expression is expected to provide insights to support inhibition of pancreatic carcinogenesis." (PMID 29245923, 2017). "The knockdown efficacies of siRNA for GPC1 were confirmed in pancreatic cancer cell lines." (PMID 29245923, 2017). "In pancreatic cancer, GPC1 is physiologically necessary for mitogenic signaling of FGF2 and HB-EGF." (PMID 29245923, 2017). "Therefore, we surmised that miRNA that regulates expression of GPC1 is downregulated in pancreatic cancer." (PMID 29245923, 2017). "A recent study suggested that GPC1 is a specific marker of exosomes in pancreatic cancer." (PMID 28233416, 2017). "The expression level of GPC1 decreased considerably after surgical resection of pancreatic cancer." (PMID 29245923, 2017).
pancreatic cancer (continued). "Although a previous study reported the successful isolation of GPC1 positive exosomes from pancreatic cancer and suggested it as a specific marker for the diagnosis and prognosis of pancreatic cancer 10, the regulations of GPC1 expression in both the tumour cells and the exosomes were not addressed." (PMID 28233416, 2017). "GPC1 + Exos was a significantly better prognostic marker of pancreatic cancer than CA19–9." (PMID 28851367, 2017). "The recent work of Melo and colleagues also showed that isolation of EVs was necessary to provide a more reliable (Glypican-1-based) diagnostic test for patients with pancreatic cancer, irrespective of the unclear intracellular origin of their marker." (PMID 27683108, 2016). "Furthermore, some secreted HSGPs, such as syndecan-1 and glypican-1, are increased in a variety of malignancies such as thyroid, pancreatic cancer, breast cancer and myeloma." (PMID 26488476, 2015). "In this regard, HS20 may be useful for multiple tumor types by targeting different glypicans, such as GPC1 in pancreatic cancer, GPC2 in pre-B cell ALL, and GPC5 in rhabdomyosarcoma." (PMID 26332121, 2015). "Glypican-1 on circulating exosomes may be an efficient non-invasive screening tool for pancreatic cancer, and exemplifies the possibilities of exosomes for cancer diagnostics." (PMID 27088079, 2015). "Monitoring glypican-1 on circulating exosomes demonstrated specificity and sensitivity in distinguishing between healthy subjects and patients with benign pancreatic cancer from early/late stage pancreatic cancer patients." (PMID 27088079, 2015). "In patients with pancreatic cancer, the cell membrane anchor protein GPC1 is specifically overexpressed in the blood vesicles; its sensitivity and specificity in the diagnosis of pancreatic cancer are 100%, and the elevation of GPC1 in the blood vesicles is earlier than the imaging changes." (PMID 40430942, 2025). "Furthermore, exosomal glypican-1 shows beneficial early pancreatic cancer detection sensitivity." (PMID 41303767, 2025). "Therefore, exosomal GPC-1 might be a potential biomarker for the rapid diagnosis of pancreatic cancer-related cachexia." (PMID 38689293, 2024). "In addition to miRNAs and lncRNAs, exosomes may contain other cargo helpful for cancer diagnosis; for example, the exosomal protein glypican-1 (GPC-1) is a biomarker for the diagnosis of pancreatic cancer." (PMID 38743146, 2024). "The detection of GPC1-positive exosomes (GPC1-Exos) in the serum of pancreatic cancer patients has absolute specificity and sensitivity, which can distinguish healthy subjects and patients with a benign pancreatic disease from patients with early- and late-stage pancreatic cancer." (PMID 38887233, 2024). "Moreover, the cell surface proteoglycan glypican-1 (GPC-1) is also found in exosomes extracted from pancreatic and breast cancer patients, which can also be detected in the early and late stages of pancreatic cancer compared to the serum of healthy controls." (PMID 38770216, 2024). "The detection of GPC1+ crExos in the serum of pancreatic cancer patients showed exceptional specificity and sensitivity, allowing for clear differentiation between healthy individuals, patients with benign pancreatic diseases, and those with early and advanced-stage pancreatic cancer." (PMID 38201485, 2023). "Moreover, EV have been studied in pancreatic cancer at early stages, by investigating the cargo of miRNAs, proteins and specific molecules such as the proteoglycan GPC1 (Glypican-1) found in serum of patients and revealed as a marker with high sensitivity of detection." (PMID 37542343, 2023). "According to the authors, “GPC1+ exosomes were detected in the serum of patients with pancreas cancer with absolute specificity and sensitivity, distinguishing healthy subjects and patients with a benign pancreas disease from patients with early and late stage pancreas cancer”." (PMID 37760400, 2023).
pancreatic cancer (continued). "Based on TCGA data, we found that GPC1 expression was upregulated in multiple cancers, including breast cancer, cervical cancer, bile duct cancer, colon cancer, glioblastoma, head and neck cancer, kidney papillary cell carcinoma, lung adenocarcinoma, and pancreatic cancer." (PMID 36158119, 2022). "Additional examples could be the possibility of measuring the expression of PD-L1 on the EV surface to assess patient eligibility for immunotherapy with checkpoint inhibitors or the detection of the EV surface protein GPC1, which is overexpressed in pancreatic cancer." (PMID 36514065, 2022). "Besides, an anti-GPC1 antibody conjugated with the cytotoxic agent monomethyl auristatin F, showed significant tumour growth inhibition against GPC1-positive pancreatic cell lines in vitro and in a mice xenograft obtained with patient derived-pancreatic cancer cells." (PMID 34249755, 2021). "As early as 1998, it has been reported that Glypican-1 (GPC1) was overexpressed in pancreatic cancer cells; and that Glypican-1 could regulate the metastasis and angiogenesis of pancreatic cancer cells, playing a pivotal role in the oncogenesis of pancreatic ductal adenocarcinoma." (PMID 34527051, 2021). "Therefore, diagnosis of pancreatic cancer in the early stage may be possible via exosomal GPC1 detection." (PMID 34595207, 2021). "Moreover, GPC1-positive EV levels correlated with tumour burden and the patients’ survival and were shown as a prognostic marker superior to CA 19-9, the serum biomarker currently employed in pancreatic cancer screening." (PMID 33494442, 2021). "Therefore, GPC1+ circulating TEXs could be used as a highly specific bio-marker for pancreatic cancer, to detect early stages of pancreatic cancer and facilitate possible curative surgical therapy." (PMID 31438991, 2019). "GPC1 was recently identified as elevated in exosomes prepared from the serum of patients with pancreatic cancer and may be involved in disease progression as a mediator of angiogenesis, although interestingly, a reduction of GPC1 was found to be predictive of disease in this case." (PMID 29854310, 2018). "Promoter hypomethylation may be substantially responsible for the re‐expression of the GPC1 gene because the methylation status of GPC1 was inversely moderately correlated with its mRNA levels in pancreatic tumor tissues (Pearson correlation coefficient = −0.5176; P < 0.0001)." (PMID 28440066, 2017). "The detection of GPC1 in pancreatic cancer exosomes exhibited a high specificity and sensitivity, which can be used to distinguish between patients with benign pancreatic disease and healthy individuals and between advanced‐stage pancreatic cancer and early‐stage pancreatic cancer." (PMID 28233416, 2017). "We show that LPHN–CHDC biochip with signal amplification capability could selectively and sensitively identify low expression glypican-1 mRNA in serum EVs, distinguishing patients with early- and late-stage pancreatic cancer from healthy donors and patients with benign pancreatic disease." (PMID 29162835, 2017). "Therefore, GPC1 might exert its oncogenic role by interacting with hedgehog pathway in pancreatic cancer." (PMID 29245923, 2017). "Thus, GPC1 + Exos could be used to diagnose pancreatic cancer at early and terminal stages with high accuracy and sensitivity, and as a detection index for therapy." (PMID 28851367, 2017). "For this reason, in cases of advanced pancreatic cancer, the pathogenic role of GPC1 might not be a central one." (PMID 29245923, 2017). "Glypican-1 (GPC-1): Found in serum-derived exosomes, GPC-1 demonstrates near-perfect sensitivity and specificity for early pancreatic cancer detection and is also a promising biomarker for colorectal cancer (CRC)." (PMID 40149276, 2025). "For example, the glycoprotein Glypican-1 (GPC1) on serum-derived exosomes from pancreatic cancer patients shows strong signals, making it a promising tool for early pancreatic cancer detection." (PMID 40277513, 2025).
pancreatic cancer (continued). "Although direct studies on the role of GPC1 in RMS are scarce, in other cancers, such as breast cancer or pancreatic cancer, GPC1 is involved in the regulation of several signaling pathways like FGF or TGF-β signaling." (PMID 40076757, 2025). "Glypican-1 (GPC1)-positive circulating exosomes can diagnose early and advanced pancreatic cancers with extremely high accuracy and sensitivity." (PMID 39744442, 2025). "The ML analysis revealed that the combination of GPC1 and EGFR, with low correlation, significantly improved the prediction accuracy for pancreatic cancer screening." (PMID 40598854, 2025). "Glypican 1 (GPC1) is a membrane-anchoring protein, which is highly expressed in pancreatic cancer tissue compared to normal tissue." (PMID 39056602, 2024). "Spheroid 3D culture methods yielded a higher number of exosomes which contained miRNA and Glypican-1 (GPC-1), more closely resembling the progression of pancreatic cancer." (PMID 36839984, 2023). "After analysis of the GPC-1+ exosomesin pancreatic cancer and healthy plasma using Western blot analysisand IG-TEM, we found that GPC-1 proteins are more strongly expressedon pancreatic cancer exosomes compared to healthy ones." (PMID 37470391, 2023). "The role of glypican-1 (GPC-1), a heparan sulfate proteoglycan (HSP), in pancreatic cancer diagnosis has been controversial." (PMID 38201207, 2023). "GPC1-enriched tumor exosomes contain mutant KRAS mRNA and have been indicated as a reliable biomarker for the detection of early pancreatic cancer." (PMID 36835443, 2023). "Here, we develop CAR T cells targeting glypican-1 (GPC1), an oncofetal antigen expressed in pancreatic cancer." (PMID 37031249, 2023). "Glypican-1 (GPC1), a membrane-anchored protein that is overexpressed in pancreatic cancer, is present in cancer exosomes." (PMID 35159011, 2022). "Another study suggests combined detection of exosomal GPC1, exosomal CD82, and serum CA19-9 for pancreatic cancer screening." (PMID 35159011, 2022). "A few years later, the same authors performed work on Panc-1 and T3M4, two other pancreatic cancer lines, and showed that TGF- β, activin, and BMP signaling were inhibited by GPC1, albeit in a very minor manner." (PMID 36142190, 2022). "Another study demonstrated that combined detection of exosomal GPC1, exosomal CD82, and serum CA19-9 shows excellent promise as a standard method for pancreatic cancer detection." (PMID 33747908, 2021). "More precisely this has been shown for GPC1 in pancreatic cancer cells, where syndecan-1 and GPC1 are both required for FGF2-growth factor response leading to metastasis and shedding of GPC1 cannot be compensated for by higher levels of SDC1." (PMID 33742285, 2021). "The PDACEV signature calculated as the unweighted sum of EGFR, EPCAM, MUC1, GPC1, and WNT2 signals showed an 86% sensitivity and 81% specificity in distinguishing pancreatic cancer patients from healthy controls." (PMID 33803470, 2021). "Glypican-1 (GPC-1), the cell surface proteoglycan 96, is exclusively present on exosomes from malignant cells and is overexpressed in breast and pancreatic cancers." (PMID 34234872, 2021). "Receiver operating characteristic (ROC) curves showed that the AUC of GPC1+ sEVs was 1.0, which was significantly higher than that of carbohydrate antigen 19-9 (CA19-9), a serum marker of pancreatic cancer." (PMID 34094979, 2021). "For example, glypican-1 (GPC1), a membrane-anchored protein overexpressed in several tumor types, is re-expressed in pancreatic cancer patients through hypomethylation of its promoter." (PMID 33962560, 2021). "Heparan sulfate proteoglycan, such as Glypican-1 (GPC-1), has been reported as a potential pancreatic cancer (PC) biomarker as its expression is greater in human PC than normal cells." (PMID 33499388, 2021). "Endothelial cell-derived glypican-1 promoted angiogenesis by regulating FGF2 and VEGFA in pancreatic cancer." (PMID 32825245, 2020).
pancreatic cancer (continued). "The GPC-1-ADC developed in this study showed significant tumour growth inhibition against GPC-1-positive pancreatic cells and patient-derived, GPC-1-positive pancreatic cancers." (PMID 32152502, 2020). "GPC-1-ADC showed significant tumour growth inhibition against GPC-1-positive pancreatic cell lines and patient-derived, GPC-1-positive pancreatic cancer tissues." (PMID 32152502, 2020). "It was recently shown that pancreatic cancer patients present circulating TEVs highly enriched in glypican-1 (GPC1) compared with healthy controls, this marker has been described to specifically correlate with early stage of pancreatic cancer." (PMID 31137912, 2019). "Utilization of this feature of exosomes enabled characterization of proteomes of pancreatic cancer cells and detection of enrichment in both pancreatic cancer cells and exosomes released by them in GPC1 proteoglycan (glypican 1)." (PMID 31096692, 2019). "This screening also identified CDKN1A (p21) and CDKN1B (p27) as upregulated genes by GPC1-depletion in HPDE cell lines and pancreatic cancer cell lines." (PMID 29245923, 2017). "Additionally, GPC1 has been demonstrated to be specifically enriched in tumor cell-derived exosomes in pancreatic cancer, and the GPC1+ exosome was proposed as a marker for the early diagnosis of pancreatic cancer and prediction of the prognosis in pancreatic cancer patients." (PMID 29254156, 2017). "Glypican-1 (GPC1), the cell surface proteoglycan, is overexpressed in breast and pancreatic cancers and is exclusively detected on exosomes derived from those malignant cells." (PMID 29282096, 2017). "In pancreatic cancer cell lines, overexpression of EVI1 by plasmid transfection exhibited a tendency to attenuate migration inhibition by silencing of GPC1 in PK-8 cell lines." (PMID 29245923, 2017). "They found that Glypican-1 (GPC1) is overexpressed in breast and pancreatic cancers and is found solely on exosomes derived from those malignant cells." (PMID 27941674, 2016). "Exosomal GPC1 cannot differentiate pancreatic tumors from non-tumorous controls, according to Lai and colleagues, and levels of exosomal GPC1 were only marginally reduced after resection." (PMID 40305328, 2025). "In a comparison between pancreatic cancer patients in stages I–IV, healthy individuals, and patients with benign pancreatic disease (BPD), the ROC curves showed that GPC1+ crExos acted as an almost perfect classifier, achieving an AUC of 1.0 (95% CI, 0.988–1.0)." (PMID 39596226, 2024). "Through analyzing the levels of glypican 1 (GPC1) exosomes in serum, a study involving German patients revealed that GPC1 exosomes could perfectly distinguish pancreatic cancer from healthy donors and individuals with benign pancreatic diseases." (PMID 39054529, 2024). "Thus, GPC1-Gd-ORI@HAuNCs-Cy7 NPs represent a potential theranostic basis to co-detect and successfully treat pancreatic cancer." (PMID 37981671, 2023). "Here, we found that GPC1 expression was increased in 4 of 6 NAT specimens, indicating GPC1 may play a role in pancreatic cancer tumorigenesis and/or progression." (PMID 37031249, 2023). "We found elevated GPC1 expression in pancreatic tumor tissues from low-intermediate to high levels, but absence of GPC1 labeling in normal pancreas." (PMID 37031249, 2023). "GPC1 expression is absent or low in normal healthy pancreas and is overexpressed in pancreatic cancer, where its elevated expression is correlated with poorer survival." (PMID 37880707, 2023). "In summary, the problem with exosomal glypican-1 is that it does not differentiate pancreatic cancer from benign pancreatic diseases." (PMID 37760400, 2023). "We found that cell surface GPC1 expression is not only increased in pancreatic tumor tissues but also strongly elevated in CAFs compared with normal pancreas." (PMID 37031249, 2023).